IL10 (interleukin 10)
Diseases named in the same sentence as IL10 in open-access papers (continued):
Sharing a sentence is not in itself a finding about the gene and the disease.
inflammation (continued). "Collectively, these results indicate that B cell-derived IL-10 mitigates lung inflammation and promotes LPS-induced ALI resolution." (PMID 37443161, 2023). "Our results highlight the essential role of B cell-derived IL-10 in the timely resolution of LPS-induced pulmonary inflammation/injury, setting up a theoretical foundation for the development of ways to treat and prevent bacteria-induced lung injury." (PMID 37443161, 2023). "IL-10 has been shown to protect against SLE by suppressing pathogenic Th1 responses, including IFN-γ-mediated autoantibody production and renal inflammation." (PMID 37366641, 2023). "In this study, Duan's research suggested that Pb exposure will cause the occurrence of intestinal inflammation in fish, which was confirmed by the mRNA expression changes in immune-related genes (TNF-α, IL-1β, IL-8, and IL-10)." (PMID 37731918, 2023). "In IMQ-induced chronic psoriasis, IL-10−/− mice exhibited more severe skin and systemic inflammation than WT mice." (PMID 37717073, 2023). "It is believed that IL-10, as an anti-inflammatory cytokine, plays a role in counterbalancing chronic autoimmune inflammation in AAV and other inflammatory entities, as it inhibits the Th1-type response and monocytes’ activation." (PMID 37894997, 2023). "Treatment with atorvastatin and ezetimibe completely prevented HCD-induced lung inflammation and resulted in remarkably higher IL-10 levels than those in the HCD group." (PMID 37082028, 2022). "In fact, IL-13 released by Tregs induces IL-10 secretion in IL13R+ macrophages in models of acute systemic inflammation." (PMID 36140212, 2022). "CD and UC showed an increase in IL‐10 messenger RNA (mRNA) versus controls (p < .0001) in mucosa, whereas IL‐10 protein secretion was increased in all types of intestinal inflammation (p < .001)." (PMID 36169258, 2022). "PMX administration in rats with LPS-induced neuro-inflammation improved hippocampal-dependent memory and exerted immuno-modulatory effects by increasing the production of the anti-inflammatory IL-10." (PMID 34249258, 2021). "The literature describes that IL-10 has an important role in controlling the magnitude of pulmonary inflammation, as it regulates the production of IL-4 and IL-5 by Th2 lymphocytes, in addition to regulation of mast cell-mediated IgE activation." (PMID 35185864, 2021). "M2 macrophages exert immunomodulatory functions, through the release of anti-inflammatory cytokines, such as TGF-1β and IL-10, which signal tissue remodeling and repair, leading to the resolution of pulp inflammation." (PMID 34440911, 2021). "As pulp inflammation progresses, the synthesis of IL-10 and IL-4 induces polarization of macrophages from an M1 to M2 phenotype." (PMID 34440911, 2021). "Overall, these results are evidence that the anti-inflammatory cytokine IL10 restores the ability of neurons to express synaptic plasticity probed by 10 Hz rMS in an in vitro model of LPS-induced neural inflammation." (PMID 33391287, 2020). "This idea would be consistent with previous studies in which Treg-derived IL-10 was able to suppress ILC2-driven papain-induced airway inflammation via an IL-33/mast cell axis." (PMID 32931477, 2020). "In gnotobiotic IL-10−/−; NF-κB(EGFP) mice, NF-κB induction in lamina propria mononuclear cells was associated with ulcerating colonic inflammation and bloody diarrhea." (PMID 33066557, 2020). "The human umbilical cord mesenchymal stem/Stromal cells (UC-MSCs) intravenous transplantation in the acute pulmonary inflammation induced by LPS in mice prevented the inflammatory response of macrophages and increased expression of IL-10." (PMID 32393278, 2020). "IL-4 and IL-10, Th2-type cytokines, also have been identified as an important mediator of lung inflammation in COPD." (PMID 33281913, 2020). "CD4CD8αα IELs also produce IL-10 and TGF-β, which can suppress Th1 cell-induced intestinal inflammation in an IL-10-dependent fashion." (PMID 31649659, 2019).
inflammation (continued). "Although Tregs have been known to play a central role in suppressing immune-mediated inflammation, it is possible that additional sources of IL-10 are required to restrain spontaneous gut inflammation." (PMID 31803193, 2019). "The expression of IL-10, a well-characterized anti-inflammatory cytokine, was upregulated to prevent further liver inflammation in the probiotic group." (PMID 31417535, 2019). "IL-10, an anti-inflammatory cytokine, reportedly inhibits cigarette smoke-induced pulmonary neutrophilic inflammation and TNF-α expression in mice." (PMID 29650044, 2018). "IL-4, IL-10 and IL-13, as the classic anti-inflammatory cytokines, can decrease the production of inflammatory cytokines, and thus inhibit synovial inflammation and bone damage." (PMID 28056922, 2017). "Collectively, it is suggested that the IL-10/IL-10R axis is crucially involved in the modulation of cochlear inflammation in otic fibrocytes and the protection against inflammation-mediated cochlear injury in the organ of Corti." (PMID 29056901, 2017). "Local administration of IL-10 to this respiratory site by means of intranasal administration of LL-IL-10 was able to modulate acute airway inflammation in a murine model." (PMID 29387056, 2017). "In the context of intestinal homeostasis, IL-10 and TGF-β1 are of particular importance in enforcing tolerance and genetic deletion of IL-10, IL-10R, or impairment of the pathway results in microbiota driven intestinal inflammation in mice and humans." (PMID 27446072, 2016). "The IL-10 KO mouse spontaneously develops intestinal inflammation at six to eight weeks of age and we have found that both male and female IL-10 KO mice fed control diet have impaired bone development by three months of age." (PMID 25247786, 2014). "For example, in a mouse model of ALI induced by LPS, the administrations of MSC induce more production of IL-10 and then ameliorate lung inflammation, which is eliminated by macrophage depletion or pretreatment with IL-10 antibodies." (PMID 24558433, 2014). "Frequent and concentrated sensitization induced exacerbation of lung inflammation immunologically and pathologically, and evoked intrapulmonary IL-17A and IL-10 production." (PMID 24928272, 2014). "Studies in mouse models of allergic airway inflammation have investigated the role of IL-10 intensively and found it to be an important mediator in the resolution of airway inflammation, but only few studied the production of IL-10 by macrophages." (PMID 23533311, 2013). "IL-10, IL-1β and COX-2 (encoded by IL10, IL1B, and PTGS2, respectively), are important mediators of intestinal inflammation." (PMID 24194923, 2013). "In their study, IB-MECA decreased the number of inflammatory cellular infiltrates during intestinal inflammation and normalized the level of cytokines and chemokines, especially interleukin-10." (PMID 23625750, 2013). "Both molecules are involved in immune regulation: B7-H3 preferentially dampens Th1-mediated responses, whereas ICOSL promotes IL-10 secretion by T cells and induces Tr1 cells that produce IL-10 and inhibit experimental airway inflammation in mice." (PMID 23717310, 2013). "RvD1 also up-regulated production of IL-10, a potent immunoregulatory cytokine that is reported to be essential for the resolution of lung inflammation and which is significantly decreased in sputum samples from COPD patients." (PMID 23484005, 2013). "The combination treatment of IL-10 gene and single-chain IL-12 gene plasmid also suppress the airway eosinophilic inflammation (p = 0.0278)." (PMID 16677403, 2006). "Since ISS-ODN-stimulated OVA-Mφ produced the highest levels of IL-10 and most strongly suppressed OVA-induced airway inflammation, we used these Mφ to further analyze the underlying mechanism of immunosuppression by allergen-loaded Mφ." (PMID 15538945, 2004).
inflammation (continued). "Previous studies have suggested a proinflammatory role for serotonin based on evidence obtained from mouse models of intestinal inflammation, where in an IL-10 knockout model, depletion of the serotonin transporter (SERT) significantly worsens general health and intestinal inflammation." (PMID 39894823, 2025). "HH also caused cardiac inflammation and fibrosis, especially in the OVX + HH group, which had elevated proinflammatory cytokines (IL-1β, IL-6, TNF-α) and decreased anti-inflammatory cytokines (TGF-β, IL-10)." (PMID 40108505, 2025). "Remarkably, in animal models, L. crispatus CCFM1339 substantially abated the secretion of the barrier disruption biomarker E-cadherin (from 101.45 to 82.90 pg/mL) and increased the anti-inflammatory cytokine IL-10 (35.18% vs. the model), consequently mitigating vaginal inflammation in mice." (PMID 38397477, 2024). "Additionally, the study demonstrates that 1.25(OH)2D3 mitigates MI-induced cardiac inflammation through two pathways by suppressing NF-κB signaling via inhibition of p-p65 nuclear translocation and upregulating the expression of the IL-10 gene." (PMID 39728467, 2024). "Moreover, IL-10 has been found to ameliorate cardiac inflammation and improve cardiac function by polarizing macrophages toward an anti-inflammatory phenotype." (PMID 38270118, 2023). "MDSCs’ immunomodulatory function, linked to increased Arg-1 and iNOS expression, may be involved in exacerbated lung inflammation post-anti-IL10 treatment in our model." (PMID 37443161, 2023). "IL-10 therapy has been reported to reduce the severity of liver inflammation and fibrosis." (PMID 37101651, 2023). "Furthermore, we demonstrate that adipocytes autophagy is part of the anti‐inflammatory immune response to intestinal inflammation by promoting the release of IL‐10 from adipose tissues." (PMID 36795015, 2023). "For example, multiple participants may have been afflicted with chronic muscle and bone inflammation, which could be inferred by reduced levels of IL-4 and IL-10." (PMID 35574470, 2022). "In vivo, treatment of Aspergillus-infected Il1r1–/– mice with anakinra increased the ratio of LC3-II/I and decreased p62, a ubiquitin-binding protein that is selectively degraded by autophagy; inhibited IL-6, IL-17A, IL-1β, and IL-1α production; increased IL-10; and ameliorated lung inflammation." (PMID 34847078, 2022). "Three days of exposure to Pb induced severe lung inflammation as evidenced by (a) increased the gene expression of several inflammatory cytokines and mediators such as IL-4, IL-10, iNOS, TNF-α, and TGF-α and (b) inhibited the gene expression of anti-inflammatory markers such as IL-6 and IL-8." (PMID 35482242, 2022). "Furthermore, we show that calcitriol prevents MI-induced cardiac inflammation through two mechanisms: dampening NF-κB signaling via preventing p-p65 nuclear translocation and up-regulating IL-10 gene expression." (PMID 35626713, 2022). "Intestinal inflammation is accompanied by the infiltration of CD11c+ DCs and leukocytes within the lamina propria that secrete greater amounts of pro‐inflammatory cytokines, while producing lower amounts of IL‐10." (PMID 33463911, 2021). "Additionally, CBM 588-induced protectin D1 clearly upregulated IL-10-producing CD4+ cells to control antibiotic-induced gut inflammation." (PMID 33193245, 2020). "Given that the tufted cells were vulnerable to nasal inflammation and odor deprivation, IL-10 may be produced by some cells to protect against the degeneration of tufted cells." (PMID 32220858, 2020). "Furthermore, retinoic acid is reported to induce transdifferentiation of ILC2s into IL-10-producing ILCregs during airway inflammation, while ILC2s provide a predominant and inducible source of IL-10 in the GI tract." (PMID 33424837, 2020). "In addition, IL-10−/− mice with experimentally induced airway inflammation showed an increase in IL-13 production." (PMID 32778925, 2020).
inflammation (continued). "Accordingly, Exo-d-MAPPS significantly improved respiratory function, downregulated serum levels of inflammatory cytokines (TNF-α, IL-1β, IL-12, and IFN-γ), increased serum concentration of immunosuppressive IL-10, and attenuated chronic airway inflammation in CS-exposed mice." (PMID 32257769, 2020). "Since gut microbiota has been shown to mediate systemic chronic inflammation in various diseases, we next analyzed potential correlations between the differentially abundant fecal microbiota and the inflammatory factors IL-4, IL-6, and IL-10." (PMID 31245306, 2019). "Altogether, analysis of all three intestinal inflammatory models (DSS, TNFΔARE and IL10 null mice) is consistent with the pathologic role of macrophages in gut inflammation, which may be targeted by aCSF1 and aIL34 therapeutics." (PMID 31552020, 2019). "Loss of expression of Il-10 in the lamina propria and of its receptor in lamina propria macrophages leads to a disruption of gut barrier function and to spontaneous gut inflammation in mice lacking these proteins." (PMID 31292292, 2019). "Collectively, the reductions in IL-6 and increases in IL-10 observed in the Caco-2/THP-1 model of intestinal inflammation containing SHIME suspensions suggest that the probiotics with digestive enzymes supplement affects the gut microbiome toward controlling inflammation." (PMID 30112118, 2018). "Intestinal inflammation could be prevented by parenteral administration of the IL-10, thus suggesting a crucial role of BM IL-10 on the infant intestinal homeostasis and prevention of exacerbated response to foreign antigens." (PMID 30018263, 2018). "Inner ear IL-10 expression is upregulated in experimental tympanogenic cochlear inflammation at the mRNA and protein levels; however, an intra-cochlear source of IL-10 still remains unclear." (PMID 29056901, 2017). "In addition, otic fibrocytes were found to play an immunological role in the induction of cochlear inflammation and were able to suppress chemokine production in response to IL-10." (PMID 29056901, 2017). "Moreover, the level of IL-10 in serum and IL-10 mRNA expression in lung, liver, and pancreas have been found to increase during acute pancreatic inflammation." (PMID 27314021, 2016). "One of these shared with DP8α LPL the capacity to secrete IL-10 and could prevent Th1-induced intestinal inflammation in an IL-10 dependent manner." (PMID 24714093, 2014). "Pancreatic inflammation in mice deficient in IFNAR1 ubiquitination was paralleled with an altered balance between pro-inflammatory and anti-inflammatory cytokines (e.g. TNFα and IL10) and increased expression of CCL2." (PMID 24480543, 2014). "In IL-10−/− mice, the development of intestinal inflammation was preceded by an increase in intestinal permeability, and enhancement of intestinal TJ barrier with a TJ barrier enhancing agent (AT-1001) prevented the development of intestinal inflammation." (PMID 24662742, 2014). "Therefore, since the correlation of serum IL-10 levels was more with ALT than with AST, it appears that it is more likely to be associated with liver inflammation." (PMID 23883139, 2013). "GSK-3β inhibition correlated with increased IL-10 expression, which may be relevant anti-inflammatory mechanism of this pathway, because IL-10 was reported to have a protective role in colonic inflammation." (PMID 24349609, 2013). "Furthermore, dietary fibre from vegetables, fruit and cereals are converted by colonic bacteria to short-chain fatty acids (SCFA) which have been found to affect intestinal inflammation in various ways including stimulation of IL-10 production." (PMID 24194923, 2013). "Lc. lactis producing recombinant IL-10 used in this study was efficient in suppressing lung inflammation, independently of Treg cells, since this cytokine plays a central role in the regulation of inflammatory cascades, allergen-induced airway inflammation, and nonspecific airway responsiveness." (PMID 21991534, 2011).
inflammation (continued). "The data further suggest that in the absence of macrophage-specific IL-4Rα signalling, IL-10 is able to drive mannose receptor- and Ym1-positive macrophages, associated with control of hepatic granulomatous inflammation." (PMID 20502521, 2010). "The cytokine IL-10, released by resident peritoneal macrophages, plays a regulatory anti-inflammatory role in the recruitment of leukocytes in murine models of peritoneal inflammation." (PMID 16519795, 2006). "Our results show dietary supplementation with ZnO-QDs significantly increased IL-10 gene expression, suggesting that the preventive role of ZnO-QDs against C. perfringens-induced intestinal inflammation may be attributed to its capacity to up-regulate the expression of anti-inflammatory cytokines." (PMID 40559850, 2025). "Gene expression analysis in the ileum showed that OVX significantly induced intestinal inflammation, as evidenced by increased expression of pro-inflammatory cytokines (Tnf-a, Il-1b, Il-6, and Il-17) and reduced expression of the anti-inflammatory cytokines (Il-10 and Ifng)." (PMID 41466098, 2025). "Systemic and pulmonary inflammation was measured by enzyme-linked immunosorbent assays of plasma and bronchoalveolar lavage (BAL), respectively, which included tumor necrosis factor alpha (TNF-α), interleukin 6 (IL-6), IL-10, C-X-C motif ligand 2 (CXCL2), and CXCL5." (PMID 38928327, 2024). "Therefore, the investigation of IL-23 signaling pathway in models of bacterial-induced intestinal inflammation with blocked IL-10R signaling can provide insights to understanding the immune regulations in the gut of IBD patients with dysregulated IL-10 responses." (PMID 33488580, 2020). "Furthermore, in a model of oral-intestinal allergy syndrome, challenge of mice sensitized to peanut extracts along with the administration of Gal-1 decreased intestinal allergic inflammation relative to mice sensitized to peanut extracts alone by restoring IL-10 expression in the intestine." (PMID 31214624, 2019). "Notably, in IL-10-deficient animals, OVA sensitization with Alum/CpG-adjuvant resulted in the development of neutrophilic airway inflammation associated with IFNγ production, while in IL-10/IL-12p40 double-knockout (KO) mice it was associated with IL-17 production." (PMID 28220116, 2017). "This was also associated with a significant decrease in the concentrations of IL-10, IL-37, and PPAR-α anti-inflammatory mediators (as compared to the NC-group), uncovering serious cardiac inflammation." (PMID 40672362, 2025). "A systematic review of human clinical trials carried out between 1980 and 2019 revealed that curcumin supplementation increased IL-10 levels and decreased MCP-1, TNF-α, IL-6, and CRP levels, reflecting its anti-inflammatory properties in chronic inflammation." (PMID 40420174, 2025). "The expression levels of immunomodulatory cytokines (IL-10 and IL-12) and the proinflammatory cytokine (IL-6) were significantly upregulated (p < 0.01) in zebrafish subjected to DSS-induced intestinal inflammation (model group)." (PMID 40862149, 2025). "Previous studies have found that stem cells can produce immunomodulatory cytokines such as IL-10 to inhibit proinflammatory cytokine secretions such as TNF-α and IL-1β, thereby alleviating pulmonary inflammation." (PMID 39011319, 2024). "Nonetheless, the mRNA signatures of cardiac inflammation were prevented or significantly reduced by hUC-MSC administration and, at the later time-point, an increase in the anti-inflammatory cytokine IL-10 was observed." (PMID 38659015, 2024). "IL-10 is highly relevant to IBD, as evidenced by the development of spontaneous intestinal inflammation in both IL-10−/− and IL-10Rβ−/− mice." (PMID 39795980, 2024). "The results of the present study have provided evidence that B cells in tuberculous WT C57BL/6 mice with chronic TB can promote lung granulomatous inflammation in a CD4+ T cell-dependent and IL-10-dependent manner." (PMID 36888692, 2023).